OLIG2 (oligodendrocyte transcription factor 2)
Diseases named in the same sentence as OLIG2 in open-access papers (continued):
Sharing a sentence is not in itself a finding about the gene and the disease.
cancer (41 papers, 2008 to 2025). A tumor composed of atypical neoplastic, often pleomorphic cells that invade other tissues. "After culturing in stem cell medium, the expression of cancer stem cell markers such as Nanog, Sox2, Nestin, and oligodendrocyte transcription factor 2 (Olig2) in GSC spheres was confirmed by immunostaining." (PMID 39721005, 2025). "Our results showed that ALDH1, CD44, Sox2, Olig2, BMI1, LGR4, LGR5, Integrin α6, L1CAM, and ABC transporter associated with cancer stem cells were significantly downregulated." (PMID 39721005, 2025). "OLIG2 is primarily expressed in central nervous system-related cancers, such as GBM and LGG, where it is significantly upregulated." (PMID 40282990, 2025). "GSCs showed characteristics consistent with cancer stem cells: namely, neurosphere formation; expression of stem cell markers Sox2 and OLIG2 and multilineage differentiation with markers for astrocytes (GFAP), neurons (MAP2) or oligodendrocytes (O4)." (PMID 37997289, 2024). "c-MYC also regulates key transcription factors like SOX2, POU3F2, and OLIG2, driving the reprogramming of cancer stem cells (CSCs) and fueling cancer progression." (PMID 39430761, 2024). "Over the past decade extensive studies have established functional roles of Olig1 and Olig2 in development as well as in cancer." (PMID 37274223, 2023). "It is also concerning that Olig2, a CNS-restricted transcription factor, emerges in other cancer types outside the CNS." (PMID 37274223, 2023). "Because Olig2 levels were detected outside the CNS, its expression in other types of cancers warrants further investigation." (PMID 37274223, 2023). "In collaboration with Curtana Pharmaceuticals (San Diego, CA), we generated an orally bioavailable small molecule (397 kD) Olig2 inhibitor, CT-179, the first drug targeting bHLH transcription factors for cancer treatment." (PMID 37274223, 2023). "Our work uncovers a SUMOylation-dependent regulatory mechanism of Olig2 in regulating cancer survival." (PMID 32483381, 2020). "For the mass cytometry assay, PDGFRA and OLIG2 were included as markers for progenitor cancer cells." (PMID 32641768, 2020). "Diametrically opposed, higher expression of OLIG2 modules distinguishes non–stem cancer cells from cancer stem cells consistently across these microvascular and necrosis substructures." (PMID 32383980, 2020). "Patient derived cancer stem cell tumorspheres grown in vitro had OLIG2 either knocked down with shRNA or pharmacologically inhibited with SKOG102." (PMID 26517684, 2017). "Olig2 is a key regulator of neural progenitor and cancer stem cell proliferation that promotes gliomagenesis." (PMID 23451236, 2013). "Consistent with prior reports, the cancer stem cell-enriched fractions also expressed high levels of Olig2, a marker of adult neural multipotent progenitors." (PMID 19020659, 2008). "These Olig2+ cells were also enriched after anti-VEGF therapy suggesting that anti-angiogenic therapies may select for cancer cells with the ability to co-opt the vasculature." (PMID 37060495, 2023). "Olig2 expression in other types of cancer is also plausible." (PMID 37274223, 2023). "OLIG2 level in the cells annotated as “cancer” was found only in this cluster of cells which also expressed the markers specific for astrocytes, neurons, and oligodendrocytes; however, it also was found in the cells with undifferentiated and proliferative properties." (PMID 34948016, 2021). "We found that while almost all cancer cells expressed OPC-associated signal transduction factors OLIG1, OLIG2, and PDGFRA, expression of progenitor-associated transcription factors such as SOX2 and SOX10 were highly expressed in cells expressing the MAPK programme." (PMID 31427603, 2019). "The goal here was to determine whether OLIG2 inhibition could suppress the cancer stem cells that drive GMB initiation and expansion." (PMID 26517684, 2017).
cancer (continued). "Given this evidence, we used a systems biology approach involving hierarchical gene network analysis to identify OLIG2-related pathways and genes that may influence cancer development and that inform drug development approaches for this pathway." (PMID 27447975, 2016). "There is also significant evidence for the role of OLIG2 in cancer." (PMID 27447975, 2016). "Below we describe how Olig2 may be activated during cancer progression." (PMID 37274223, 2023). "Each subpanel corresponds to one gene (ATRX, OLIG2, MGMT, and IDH2) and displays its expression levels in tumors (red) and normal tissues (blue) across multiple cancer types." (PMID 40282990, 2025). "They express cancer stem cell markers, such as CD34, MMP2, nestin, and SOX2, as well as the astro-neuronal lineage markers GALC, TUBB3 (CD56), and OLIG2." (PMID 34638987, 2021). "It is usually only expressed in type I GBM cancer stem cells and is co-expressed with the stem cell markers SOX2, SOX11 and OLIG2." (PMID 30208958, 2018). "Kaplan–Meier survival curves based on TCGA data support an OLIG2 and KDM1A (AOF2) concerted involvement in cancer development." (PMID 27447975, 2016). "In our research, significant expression of Ki-67 and Olig-2 was observed in TJ905 cells and was much higher in TJ905 stem cells, which demonstrated that the malignant degree in cancer stem-like cells." (PMID 26136642, 2015). "In addition, CPZ was able to downregulate the expression of OCT 3/4, SOX2, NANOG, Nestin, OLIG2 and ALDH1A3, universal cancer stem cells genes for GBM." (PMID 33718225, 2021). "However, abundant CD163 staining cannot rule out cancer recurrence if areas of Olig2+ nuclear atypia with notable Ki67 positivity are present." (PMID 38049893, 2023). "In GBM cell population, SOX2, along with POUF3F2, SALL2 and OLIG2, forms a group of core transcription factors that triggers an epigenetic effect in cancer cells leading to a formation of tumor propagating cancer stem-like cells, making SOX2 a good candidate for cancer stem cell marker." (PMID 32092088, 2020).
infection (14 papers, 2010 to 2025). The state of being infected such as from the introduction of a foreign agent such as serum, vaccine, antigenic substance or organism. "A 30% reduction in OLIG2-positive cells was observed in infected as compared with uninfected cultures, showing that infection also affected oligodendrocyte survival." (PMID 41419758, 2025). "RSMHV2 infection was restricted to the gray matter whereas Olig2 stained cells were observed in both gray and white matter." (PMID 26733813, 2015). "Flag+/Pax6+ cells, which were Olig2+ at the time of infection, migrated tangentially and were also localized to the SVZ (∼42%), RMS (∼41%) and olfactory bulb (∼2%)." (PMID 21698109, 2011). "Six days after infection, the cultures were immunostained for Olig2 to quantify the percentage of differentiating OPCs." (PMID 20939912, 2010). "Using immunohistochemistry, we examined AAV infection of oligodendrocytes with immunofluorescence for GFP and OLIG2, an oligodendrocyte marker." (PMID 40043106, 2025). "Other glial cell types, including OLIG2+ oligodendrocyte precursor cells and IBA1+ microglia, also demonstrated minimal capacity for infection." (PMID 35858406, 2022). "Before the infection with HSV-1, COs were characterized by IHC for brain cell types including neurons, microglia, astrocytes, and oligodendrocytes using MAP2/TUJ-1-, IBA1-, GFAP-, and Olig2-specific antibodies, respectively." (PMID 39176174, 2024). "Unfortunately, we obtained no information on oligodendrocytes infection or on oligodendrocytes ultrastructural changes as both anti-Olig2 abs failed to target the oligoglial cells." (PMID 35203160, 2022). "According to our protocol, infection was performed on the hiPSC level; subsequent puromycin selection was performed to enrich for S-, SO-, or SON-hiPSC and followed by neural induction to generate PAX6+ and OLIG2+ neural precursor cells (NPCs)." (PMID 35053357, 2022). "The proportion of hippocampal OLIG2+ IL-33+ cells was sharply increased on day 7 post PbA-infection in WT mice, but not in ST2-/- infected mice." (PMID 28448579, 2017).
psychiatric disorder (5 papers, 2015 to 2025). A disorder characterized by behavioral and/or psychological abnormalities, often accompanied by physical symptoms. "In fact, some oligodendroglia specific risk factors (e.g., OLIG2, SOX10, and CNP), which are crucial for oligodendroglia development and myelination, are robustly dysregulated in major mental illnesses." (PMID 30524471, 2018). "Concordant with the increased inflammatory signal, there was a downregulation in mRNA expression of genes linked to neurodevelopment and myelination, neurotransmitter regulation, and psychiatric disorders including calcium binding Calb2 and S100b, as well as SNAP25, Pvalb, MAG, Olig1, and Olig2." (PMID 40059770, 2025).
CNS tumor (4 papers, 2019 to 2025). "The recently described entity “CNS tumor with PLAGL amplification” (particularly PLAGL2 in infants and toddlers) also shows overlapping embryonal features with the tumors in this series, nonetheless with a different immune-profile—OLIG2 being mostly negative, and synaptophysin being patchy and weak." (PMID 38500181, 2024).
neurological diseases (3 papers, 2005 to 2020). "Both signatures included a number of genes (MBP, MOBP, MAG, OLIG1, and OLIG2) previously found in glial cells, several of which have been linked to neurological diseases." (PMID 16168081, 2005).
OLIG2 also shares sentences with these, for which no sentence is quoted: chordoma (2 papers); diffuse astrocytoma (2); hemangioblastoma (2); Intellectual disability (2); neurodegenerative disease (2); adenocarcinoma (1); amyotrophic lateral sclerosis (1); Atrophy (1); B-cell lymphoma (1); B-cell neoplasm (1); bipolar disorder (1); breast carcinoma (1); cerebral amyloid angiopathy (1); cerebral artery occlusion (1); CNS germ cell tumors (1); CNS lymphoma (1); cognitive disorder (1); Fanconi anemia (1); focal epilepsy (1); frontal lobe epilepsy (1); ganglioglioma (1); gastrointestinal tumors (1); germinoma (1); holoprosencephaly (1); lentivirus infection (1); leukoaraiosis (1); lymphatic diseases (1); lymphoma (1); microcephaly (1); mood disorder (1).
A further 19 diseases each share a sentence with OLIG2 in 1 paper.